AFP (alpha fetoprotein)
Diseases named in the same sentence as AFP in open-access papers (continued):
Sharing a sentence is not in itself a finding about the gene and the disease.
Cirrhosis (continued). "Compared with ICC patients without HBV infection, those with HBV infection were 7 years younger and had a higher male-to-female ratio, higher proportions of positive AFP, cirrhosis, and MVI and lower proportions of PLR (>117) and advanced Child–Pugh score (B vs. A)." (PMID 31179237, 2019). "Binary logistic regression analysis was conducted to evaluate the contribution of combined measurement of miRNA-215 and AFP to assign individuals to the outcome disease whether cirrhosis or HCC." (PMID 31554369, 2019). "Similarly, CHC patients with HBV infection were 9 years younger and had higher proportions of AFP positivity and cirrhosis, and lower proportions of NLR (>3.3) and PLR (>117) than those without HBV infection." (PMID 31179237, 2019). "In the stratification of HLA-DQA1 for OS analysis, high expression showed significance in males, age ≤ 60 years, active viral replication-chronic carriers of HBV, cirrhosis, single nodular, low AFP levels (≤ 300 ng/ml) and A stage of the BCLC system compared with low expression." (PMID 31602270, 2019). "Survival analysis showed that AFP is a risk factor for prognosis in both patients with and without cirrhosis." (PMID 30886700, 2019). "In order to confirm the risk factors of RFS in HCC patients, Cox proportional hazard analysis was performed with clinical factors (age, gender, maximum tumor size, MVI, cirrhosis, differentiation, HBsAg status, and AFP) and preoperative serum IL6, IL8, and TNF-α levels." (PMID 31781194, 2019). "FLC is typically found in adolescents and young adults without underlying liver disease, such as viral hepatitis or cirrhosis, and elevations in serum alpha fetoprotein (AFP) are not typically seen." (PMID 29535801, 2018). "We used electronic medical records from the Department of Veterans Affairs Hepatitis C Clinical Case Registry to construct our analysis cohort, which consists of serial AFP tests in 11,222 cirrhosis control patients and 902 HCC cases prior to their HCC diagnosis." (PMID 29301497, 2018). "In a case-control study of 163 HCC patients with HCV infection and 149 control patients with HCV-related cirrhosis, the sensitivity of AFP for the diagnosis of HCC in AA with HCV infection was reported to be lower than that of patients of all other ethnic groups combined." (PMID 29538406, 2018). "We had to exclude other clinically relevant features like differentiation, size, cirrhosis and alpha-fetoprotein (AFP) levels because these were only published for a few patients—a robust multivariate analysis can only take account of patients where all data are simultaneously available." (PMID 30662724, 2018). "The most important risk factors for HCC irrespective of underlying cirrhosis etiology were older age, male sex, Hispanic ethnicity, high serum AFP level, alkaline phosphatase level and AST/√ALT ratio, and low platelet count and serum albumin level." (PMID 30260995, 2018). "Therefore, further research about the relationship among AFP, hepatitis or cirrhosis and PHSC needs to be done with a larger sample in the future." (PMID 30314525, 2018). "Taken together, it can be suggested that consideration of age, sex, status of cirrhosis and AFP levels along with US results improves the screening accuracy of HCC detection, probably by identifying additional patients for whom dynamic imaging studies are likely to produce positive results." (PMID 29290966, 2017). "Elevated AFP levels may be seen in patients with cirrhosis or exacerbation of chronic hepatitis or cholangiocarcinoma (low specificity)." (PMID 28077782, 2017). "Based on the univariate analysis, the significant prognostic factors for survival included cirrhosis (P = 0.0086), the histologic grade (P = 0.0382), AFP (P < 0.0001), the pathological stage (P = 0.0054), the clinical stage (P < 0.0001), vascular invasion (P < 0.0001) and the MPM-BC (P = 0.0052)." (PMID 28031532, 2017).
Cirrhosis (continued). "By multivariate analyses, independent predictors of early recurrence in the overall cohort were BMI >27.5 kg/m2 (HR = 2.185, p = 0.010), BCLC stage B-C (HR = 2.526, p = 0.001), serum AFP level >20 ng/mL (HR = 2.212, p = 0.006) and histological cirrhosis (HR = 2.989, p<0.001)." (PMID 29176777, 2017). "Moreover, serum Alpha-fetoprotein in HCC patients with cirrhosis decreased sharply after resection of tumor tissue, while the serum GP73 remained stable." (PMID 28157705, 2017). "Various studies aimed at developing a simple validated prognostic score based on different predictive factors (scoring system, number and size of hepatic lesions, AFP value, and cirrhosis pathogenesis) of survival and TACE response in patients with HCC treated with TACE." (PMID 28894464, 2017). "Next we investigated the diagnostic value of sAxl in HCC and cirrhosis with and without incorporation of the established serum marker AFP." (PMID 28526812, 2017). "The total number of lesions, gender, subcapsular location of the lesion, cause of the cirrhosis, Child-Pugh score, T2-weighted signal intensity, and AFP level at baseline did not significantly influence the response rate." (PMID 28441447, 2017). "By multivariate analyses, independent predictors of RFS were female sex (HR = 0.197, p = 0.024), BMI >27.5 kg/m2 (hazard ratio (HR) = 1.882, p = 0.012), BCLC stage B-C (HR = 1.573, p = 0.046), serum AFP level >20 ng/mL (HR = 2.082, p = 0.001) and histological cirrhosis (HR = 2.257, p<0.001)." (PMID 29176777, 2017). "Additionally, among the HBV infection-related patients, the median serum AFP level in HCC patient group was significantly higher than that in CHB or cirrhosis patient (423.89ng/ml vs 40.82ng/ml, P < 0.000)." (PMID 26784252, 2016). "Second, the serum AFP concentration might be influenced by hepatitis, cirrhosis and liver cell necrosis." (PMID 26831408, 2016). "Additionally, gender, tumor size, HBeAg levels, histological grade, AFP levels, intrahepatic metastasis, hepatic cirrhosis, and lesion location were roughly identified as irrelevant factors for the prognosis of HCC patients after operation." (PMID 27079415, 2016). "Univariate ROC analysis identified covariates which affected surveillance performance of AFP: the c-statistics were lower in patients with cirrhosis, elevated AST levels, low albumin levels, prolonged prothrombin time, elevated baseline AFP levels, and exposure to NA therapy during study period." (PMID 27997559, 2016). "Increased production of AFP in hepatitis and cirrhosis was first thought to reflect the process of surviving hepatocytes, but this hypothesis has been refuted by other reports." (PMID 26640716, 2015). "Furthermore, the SEER database lacks important information regarding LC predisposing factors (e.g., viral hepatitis, non-alcoholic fatty liver disease, or cirrhosis), cancer treatment (chemotherapy, quality of surgery), as well as alpha-fetoprotein levels." (PMID 25575810, 2015). "Moreover, the specificity of AFP for HCC is low since elevated AFP is also detected in the serum of patients with cirrhosis and hepatitis." (PMID 28943622, 2015). "Clinical variables entered after PSM were age, gender, tumor size, hepatitis B virus (HBV) infection status, Child-Pugh class, cirrhosis, total bilirubin, serum AFP level, alanine aminotransferase (ALT), aspartate aminotransferase (AST), prothrombin time, albumin and platelet count." (PMID 25541684, 2014). "At baseline, patient 8 was free active disease but positive for cirrhosis, had normal AFP (5 ng/ml), had Karnofsky performance status 80%, was Child-Pugh A, HLA-A2+, and had intermediate detectable levels of anti-AdV neutralizing antibodies which were in the acceptable range for trial enrollment." (PMID 24708667, 2014).
Cirrhosis (continued). "We further examined possible associations between the levels of ARPP-19 mRNA and the clinicopathologic parameters of the HCC patients, including age, gender, etiology, maximal tumor size, histologic grade, presence of cirrhosis and serum alpha-fetoprotein (AFP) concentration." (PMID 25547487, 2014). "However, other variables including age, sex, cirrhosis background, capsular infiltration, serum AFP level, HBsAg status and multinodular tumor seemed to show a general trend, with subtle differences in survival without significance." (PMID 24885292, 2014). "In this study, we analyzed serum levels of alpha fetoprotein, Golgi protein, fucosylated alpha-1-anti-trypsin, and fucosylated kininogen from 113 patients with cirrhosis and 164 serum samples from patients with cirrhosis plus HCC." (PMID 24564861, 2013). "AGP was useful for discrimination of HCC from cirrhosis in patients with AFP less than 500 ng/mL." (PMID 23401773, 2013). "However, its sensitivity for detecting HCC ranges between 25%-60%, and its specificity is also low because serum AFP can also be detected in patients with cirrhosis (11%-47%) and chronic hepatitis (15%-58%)." (PMID 24252133, 2013). "The authors retrospectively assessed serum DKK1 in 1284 patients (633 with HCC, 171 with chronic HBV infection, 168 with cirrhosis, and 312 healthy controls) and found that DKK1 has better diagnostic value for HCC than does AFP, especially for patients with AFP-negative and early stage HCC." (PMID 24252133, 2013). "AFP level may be elevated in patients with chronic liver disease such as hepatitis or cirrhosis, or patients with drug or alcohol abuse, but in these cases the level is usually <100 ng/mL." (PMID 22559879, 2012). "Since the group with steatosis has more fibrosis/cirrhosis than group without steatosis, hence, the joint association observed in this study among increased AFP in chronic HCV with steatosis than none steatotic group." (PMID 22675639, 2012). "An increase of serum AFP levels can be observed during pregnancy, and in patients with mucoviscidosis, acute hepatitis (30%–50%), chronic hepatitis (15%–50%), cirrhosis (11%–47%) and other cancers (gastrointestinal, pancreatic, biliary, nonseminomatous germ-cell testicular, and germ cell ovarian)." (PMID 22690340, 2012). "The persistently elevated AFP level after hepatectomy in the current patient cannot be explained by exacerbation of an underlying disease, because he did not have hepatitis or cirrhosis." (PMID 22559879, 2012). "Benign circumstances that may produce elevations of AFP include cirrhosis, hepatic necrosis, acute hepatitis, chronic active hepatitis, ataxia-telangiectasia, and pregnancy." (PMID 22675639, 2012). "Most patients had alpha-fetoprotein levels of at least 100 ng/mL, and 46% had cirrhosis." (PMID 19193234, 2009). "In this study, we have determined serum PIVKAII and GGTII levels in patients with HCC or cirrhosis using ED036 kit and polyacrylamide stage gel plate, respectively, in order to assess the diagnostic values of PIVKAII, GGTII combined with AFP for clinical application." (PMID 12799630, 2003). "In conclusion, both 3% PEG-CICs and AFP are independent risk factors of HCC, and may be used as complementary tumour markers to discriminate HCC from cirrhosis." (PMID 7543774, 1995). "However, AFP is positive in only 60%-80% of HCCs, and AFP can be elevated in other benign or malignant conditions, such as chronic hepatitis, cirrhosis, intrahepatic cholangiocarcinoma and embryogenic tumors, leading to an unreliable role of AFP in surveillance." (PMID 41584034, 2026). "Furthermore, results involving AFP in CHC patients diagnosed with cirrhosis are contradictory." (PMID 40384539, 2025). "We conducted a cost-effectiveness analysis to evaluate four surveillance strategies (no surveillance, universal US + AFP surveillance, risk-stratified surveillance, and precision surveillance) in a simulated cohort of 50-year-old patients with compensated cirrhosis." (PMID 39234558, 2024).
Cirrhosis (continued). "Considering both the benefits and harms related to surveillance, utilizing ultrasounds in conjunction with AFP testing proved to be a more cost-effective approach for monitoring HCC than relying on ultrasounds alone or foregoing surveillance entirely in individuals with compensated cirrhosis." (PMID 39410020, 2024). "Several factors, including older age, male gender, alpha-fetoprotein (AFP), aspartate aminotransferase (AST), alanine transaminase (ALT), gamma-glutamyl transferase (GGT) and total bilirubin, were reported to be associated with the increased risk of HCC in patients with HCV or cirrhosis." (PMID 38007418, 2023). "No other cause for AFP elevation was found such as hepatitis or cirrhosis." (PMID 36816961, 2023). "Finally, 18 variables (age, tumor size, CTP, cirrhosis, HBsAg, AFP, TB, resection method, SAT density, VAT area, VAT density, VATI, VSR, IMAT area, IMATI, SM area, SM density, SMI) with nonzero coefficients were selected according to the value of lambda.min (λ = 0.03139931)." (PMID 37794517, 2023). "AFP may increase the sensitivity of USG when used in combination in patients with cirrhosis." (PMID 37568696, 2023). "Therefore, one can envision that AFP-based vaccines might be helpful in preventing or significantly delaying the onset of HCC in this population, particularly at-risk patients who have cirrhosis and are enrolled in a radiographic screening program." (PMID 37040183, 2023). "Smoking, alcohol consumption and DM stood out as independent factors for isolated cirrhosis; while for cirrhosis with HCC alcoholism, DM, age, male gender, presence of polymorphic allele of CYP24A1-rs6013897 (_/T), viral hepatitis and altered serum levels of GGT, AFP and creatinine were the factors." (PMID 35919232, 2022). "Therefore, it may be used as a screening indicator for patients with hepatitis or cirrhosis with low AFP levels." (PMID 35712125, 2022). "Serum AFP could be elevated in other tumors or chronic liver disease and cirrhosis." (PMID 36117166, 2022). "This group had a higher diagnostic ability than AFP in differentiating HCC from high-risk patients with cirrhosis, identifying HCC patients with false-negative AFP, screening small HCC (s-HCC) patients from high-risk patients, and distinguishing HCC from other cancers." (PMID 36532884, 2022). "When combined with serum AFP detection (AFP > 20 ng/mL), the sensitivity/specificity of aberrant fucosylation test for HCC improved to 78/88%, 85/88%, and 89/91% in all serum samples, HBV-associated chronic liver diseases and HBV-associated cirrhosis, respectively." (PMID 33562077, 2021). "The combination of hsa_circ_0028861 and AFP exhibited better diagnostic performance than AFP alone in differentiating HCC patients from chronic HBV patients (AUC: 0.91 vs. 0.82), cirrhosis patients (AUC: 0.82 vs. 0.69), or the combination of chronic HBV and cirrhosis patients (AUC: 0.86 vs. 0.76)." (PMID 34367259, 2021). "Furthermore, heterogeneity tests revealed that heterogeneity was substantial in the following cases: AFP (I2 = 86.14%, Q-test p = 0.01), cirrhosis (I2 = 87.81%, Q-test p = 0.00), invasion (I2 = 80.92%, Q-test p = 0.00) and TNM staging (I2 = 95.72%, Q-test p = 0.00)." (PMID 34771514, 2021). "Furthermore, high Elafin expression was significantly associated with high alpha-fetoprotein levels, cirrhosis, multiple tumours, lack of a tumour capsule, tumour thrombus, and adjacent organ invasion (all P < 0.05)." (PMID 33771199, 2021). "Furthermore, we observed significant positive correlations of AFP with gender and cirrhosis." (PMID 31973032, 2020). "The prognostic risk factors that may predict the outcome of survival, including sex, serum AFP level, cirrhosis, TNM stage, tumor size, and cell cycle gene expression, were selected to construct the nomogram, which can provide an individualized prognosis prediction." (PMID 32596342, 2020).
Cirrhosis (continued). "Thus, the aims of this study were to describe the clinical characteristics of ESLD patients in Ghana, and to assess the utility of the aspartate aminotransferase (AST)—platelet ratio index (APRI) score and alpha fetoprotein (AFP) in diagnosis of cirrhosis and HCC among this cohort." (PMID 33357229, 2020). "This is supported by another study that reveals the combination of AFP plus ultrasonography is higher sensitivity than ultrasonography alone for early HCC detection in patients with cirrhosis 9 further suggesting that other combinations may possibly improve the diagnostic accuracy of HBV‐HCC." (PMID 32150664, 2020). "The algorithm based on levels of AFP, platelets, and alanine aminotransaminase (ALT), along with age, could predict whether HCC is likely to develop within 6 months in patients with hepatitis C virus-associated cirrhosis." (PMID 32038998, 2019). "To test whether the gene signature is independent of other prognostic factors, including sex, age, cirrhosis status, AFP, TNM staging, BCLC staging, and BMI in the validation cohorts, we performed Cox regression analysis in the LEC, TCGA-LIHC and the Korean datasets." (PMID 30833661, 2019). "Therefore, comprehensive detection and evaluation using multiple factors (e.g., miR-122 and miR-148a combined with AFP) may be able to more accurately distinguish early HCC from cirrhosis." (PMID 31815633, 2019). "However, miR-501-3p expression level was not significantly correlated with other clinical characteristics, including age, sex, hepatitis B surface antigen, preoperative alpha-fetoprotein, gamma glutamyl transferase, cirrhosis, tumor number, tumor encapsulation, or tumor differentiation." (PMID 29749382, 2018). "However multi nodular tumours (P = 0.992), large tumour diameter (P = 0.155) and presence of background cirrhosis (P = 0.694), history of alcohol consumption did not have a significant association of having an AFP level above 400 ng/ml." (PMID 29207969, 2017). "Additionally, serum AFP levels of benign liver diseases, including hepatitis and cirrhosis, may give false-positive results." (PMID 29113383, 2017). "Interestingly, sAxl outperformed AFP in diagnostic performance in both HCC and cirrhosis." (PMID 28526812, 2017). "In addition, chronic hepatitis or cirrhosis raise AFP in 20% and 40% of patients, respectively." (PMID 28031532, 2017). "However, AFP has suboptimal performance as a serological test for surveillance of HCC because it depicts fluctuating levels in patients with cirrhosis with a flare of HCV or HBV infection, in exacerbations of the underlying liver disease, or with the occurrence of HCC." (PMID 28620797, 2017). "Furthermore, the diagnostic capability of DCP in discriminating AFP-negative HCC patients with a cirrhosis background from LC patients was investigated." (PMID 27070780, 2016). "Although many studies concluded that non-SVR, older age, higher pre/post treatment ALT and AFP levels, and cirrhosis were associated with HCC occurrence, few reports focused on the relationship between insulin resistance and HCC occurrence, especially for non-cirrhotic patients." (PMID 26913058, 2016). "In addition, a significant increase in serum AFP level (20–200 ng/mL) is detected in a considerable number of patients with chronic liver disease, including 15%–58% of patients with chronic hepatitis and 11%–47% with cirrhosis." (PMID 25871387, 2015). "In addition, it may have a value complementing that of AFP, which is predominantly elevated in patients with advanced HCC, in highlighting individuals with cirrhosis who are at greater risk of HCC development." (PMID 19656391, 2009). "Among HCC patients exhibiting AFP levels below 200 ng/mL, SNHG18 shows comparatively high sensitivity and specificity relative to cirrhosis patients and healthy controls, with sensitivity at 75.61% and specificity at 73.49%." (PMID 41474641, 2026).